AFP (alpha fetoprotein)
Diseases named in the same sentence as AFP in open-access papers (continued):
Sharing a sentence is not in itself a finding about the gene and the disease.
tumor (continued). "High AFP level, multiple tumor nodules, microvascular invasion, poor tumor differentiation, portal lymphatic invasion, and high GSC expression were all found to be associated with shorter time to lung metastasis by univariate analysis." (PMID 25343336, 2014). "Evidence for an AFP-mediated induction of tolerogenic DCs came from a tumor model where AFP has been demonstrated to induce tolerogenic DC capable of suppressing tumor-specific CD8+ cytotoxic T lymphocytes within the tumor." (PMID 24847324, 2014). "Serum AFP level is useful in diagnosing tumor recurrence and predicting prognosis in HCC patients treated by hepatic resection, transarterial chemoembolization, and radiofrequency ablation." (PMID 24993566, 2014). "By contrast, circulating AFP concentration was correlated with the levels of AFP mRNA in tumor cells (P = 0.0001)." (PMID 25502816, 2014). "For the patient of the present case, several tumor markers were significantly elevated but alpha-fetoprotein was normal." (PMID 24893802, 2014). "The multivariate Cox proportional hazards model identified tumor number (≥3), serum AFP (≥400 ng/mL), macrovascular invasion, major hepatectomy, and PHT as mortality risk factors." (PMID 25268959, 2014). "Patients with TRIM24 overexpression showed poor differentiation, higher level of AFP, higher incidence of intrahepatic metastasis and recurrence, and shorter Tumor-free survival time." (PMID 24409330, 2014). "We analyzed the correlation between ZDHHC2 mRNA expression and clinical parameters including age, preoperative serum AFP level, tumor number, tumor size, PVTT, and histopathologic grading." (PMID 24995331, 2014). "Univariate analysis demonstrated a significant impact of clinicopathologic prognostic features (i.e., AFP levels, tumor size, tumor multiplicity, clinical stage, vascular invasion and relapse) on the patient survival rates (P<0.05)." (PMID 24475046, 2014). "The clinical use of octreotide LAR has been shown to be useful in a patient with metastatic HCC, in which it improved quality of life (QoL) and reduced AFP levels and tumour size." (PMID 25225571, 2014). "We next analyzed clinical features (including AFP level, tumor size, tumor multiplicity, stage and vascular invasion) and PTPN12 expression that displayed significant impact on patient survival based on univariate analyses with Cox proportional hazards model." (PMID 24475046, 2014). "We also evaluated the relationships between 3-month post-treatment serum AFP levels and recurrent tumor size." (PMID 24993566, 2014). "In this setting, a retroperitoneal tumor should be investigated by specific tumor markers such as alpha-fetoprotein and β-human chorionic gonadotropin." (PMID 25431731, 2014). "The results revealed that a high level of miR-130b expression was correlated with serum a-fetoprotein (AFP) level (P = 0.04), HBsAg status (P =0.02), tumor size (P = 0.04), high histologic grade (P =0.005), and high TNM stage (p < 0.001)." (PMID 25123453, 2014). "The current meta-analysis showed that a high NLR correlated closely with vascular invasion and an elevated AFP level, both of which are known to be correlated with invasion of tumor cells and to be prognostic factors for poor survival of patients." (PMID 24788770, 2014). "Among these anti-correlated glycolytic genes, the PK transcript level was significantly associated with the overall survival time of HCC patients, as well as the serum alpha-fetoprotein level, histological differentiation of tumor tissue, and TNM stage." (PMID 24466275, 2014). "Tumor cells of the intermediate cell subtype of c-HCC-CCs express hepatocytic markers (AFP or HepPar-1), biliary markers (K7 or K19) and/or putative stem cell markers (CD56, CD133 or EpCAM)." (PMID 25202388, 2014). "IDH2 expression correlated with HBsAg (P =0.015), AFP (P <0.001), and tumor differentiation (P =0.015)." (PMID 24716838, 2014).
tumor (continued). "Univariate analyses of prognostic factors showed that Nodal expression, gender, AFP, ICGR15, vascular invasion, tumor size and Edmondson grade are associated with a significant prognostic effect on OS (P<0.05)." (PMID 24465741, 2014). "Equally important to note is that apart from AFP level and tumor staging classification such as the Barcelona Clinic Liver Cancer (BCLC) staging system, there is no good prognostic marker that can classify patients and predict survival outcome." (PMID 24635883, 2014). "Elevated TRIM24 level was found in 61.4% HCC samples (51/83) correlating with AFP (P = 0.036), poor differentiation (P = 0.004), intrahepatic metastasis (P = 0.004), recurrence (P = 0.000006), and shorter tumor-free survival time (P = 0.002)." (PMID 24409330, 2014). "The results showed that CTSL expression, serum AFP, tumor size, tumor recurrence and stage were recognized as independent prognostic factors of survival." (PMID 25384089, 2014). "We also detected significant correlations between low IDH2 expression and HBsAg background, a high level of AFP, and low-grade tumor differentiation." (PMID 24716838, 2014). "Retroperitoneal teratomas can express a diversity of serum tumor markers such as elevated AFP, CEA, and CA 19-9." (PMID 25506459, 2014). "The statistically significant correlations were observed between nucleolin expression and tumor stage, tumor grade and serum AFP level." (PMID 25230759, 2014). "The presence of ascites, multiple focal lesions, large tumour size, portal vein thrombosis, extrahepatic spread, AFP level and CTP score were independent predictors of survival." (PMID 24603710, 2014). "Evaluation of the solid scrotal mass includes: scrotal ultrasound; chest, abdominal, and pelvic computed tomography (CT); and determination of serum tumor marker levels such as alpha-fetoprotein (AFP) and beta-human chorionic gonadotropin (β-hCG)." (PMID 25547829, 2014). "Both patients were successfully vaccinated, but patient 7 expanded only AdV-specific T cells and recurred earlier with an AFP-positive tumor." (PMID 24708667, 2014). "In our case the tumor was located on the liver and there was a high serum level of AFP and our initial diagnosis was HCC." (PMID 24715921, 2014). "Cox regression analyses revealed that higher levels of PHD2, tumor size, tumor stage, as well as serum AFP level were predictors for a worse prognosis in patients with HCC." (PMID 25546659, 2014). "The tumour markers are mainly increased by: carcinoembryonic antigen, alpha-fetoprotein, and the chorionic gonadotropin beta fraction; the tumours in ovarian germ cells represent 20% of the neoplasms where only 3% is associated with malignancy." (PMID 25371706, 2014). "Multivariate analysis confirmed that tumor diameter (P = 0.045, hazard ratio [HR]: 0.228, 95% confidence interval [CI]: 0.054-0.968) and pretreatment serum AFP level (P = 0.024, HR: 2.239, 95% CI: 1.114-4.500) were independent predictors for survival." (PMID 24410841, 2014). "Prognostic factors identified in previous studies include tumor stage, serum α-fetoprotein (AFP), vascular invasion, tumor size, and poor tumor differentiation." (PMID 25280428, 2014). "Alpha fetoprotein (AFP) usually correlates with tumor size and doubling time of AFP correlates with the tumor doubling time." (PMID 25120882, 2014). "HCC patients who had an AFP+ tumor and previous treatment for HCC were screened and two patients received vaccination with three plasmid DNA injections followed by a single AdV injection, all delivered intramuscularly (i.m.)." (PMID 24708667, 2014).
tumor (continued). "Our study revealed that the increased expression of nucleolin was dramatically associated with aggressive clinicopathological features of patients with HCC, such as advance tumor stage, high tumor grade and high serum level of AFP." (PMID 25230759, 2014). "In the validation cohort, 5-hmC expression correlated with sex (P =0.003), age (P =0.034), AFP (P <0.001), tumor number (P =0.02), and TNM stage (P =0.009)." (PMID 24716838, 2014). "Screening for tumour markers alpha fetoprotein, carbohydrate antigen 19-9 and carcinoembryonic antigen are usually negative." (PMID 25505821, 2014). "Serum interleukin-2 receptor was elevated at 3720 U/mL (145–519 U/mL), but the levels of other tumor markers, such as alpha-fetoprotein (AFP) and carcinoembryonic antigen (CEA), were normal." (PMID 25610674, 2014). "Except for the elevation of AFP serum levels, the tumor markers, including carcinoembryonic antigen, carbohydrate antigen 125, squamous cell carcinoma antigen, neuron-specific enolase and cytokeratin (CK) 19 fragment, were within the normal ranges." (PMID 24959228, 2014). "Change in serum AFP levels (defined as a >50% decrease compared with baseline) after locoregional therapy are reportedly useful in assessing tumor response and survival, and for assessing lesions that have progressed on imaging examinations." (PMID 24993566, 2014). "The prognostic relevance of AFP and tumor size for DFS in HCC patients was confirmed by previous studies." (PMID 25431949, 2014). "The pre-treatment serum AFP level and tumor size, 3-month post-treatment serum AFP level, and time of any tumor recurrence were recorded." (PMID 24993566, 2014). "The tumor markers were alpha fetoprotein: 2.5ng/mL (reference value (RV): up to 7ng/mL), beta-HCG: normal (RV: <3U/mL) and lactate dehydrogenase: increased 483UI/L (100 a 190UI/L)." (PMID 24728256, 2014). "LY2157299 treatment was associated with AFP responses, reduction in TGF-β1 and E-cadherin levels, and time to tumor progression was increased in patients with AFP and TGF- β1 levels reduction from baseline." (PMID 24393789, 2014). "Despite a relatively small tumor size (21 mm in diameter), the patient’s serum AFP level was extremely high (9176 ng/ml)." (PMID 26034695, 2014). "The evidence for routinely sending serum tumor markers such as AFP, LDH, and beta-hCG for screening purposes in patients with XY PGD is lacking." (PMID 24731683, 2014). "Taken together, significant associations were found between HCC recurrence and the following variables: LOH on ZDHHC2, preoperative AFP level >400 ng/mL, tumor size >5 cm, and presence of PVTT." (PMID 24995331, 2014). "Our data show that higher PHD2 expression in tumor is correlated to tumor stage, tumor diameter, and serum AFP levels in patients with HCC." (PMID 25546659, 2014). "If the patient has a gonadal mass on pre-operative imaging and/or discordant pubertal characteristics, consider serum tumor markers, including AFP, LDH, and beta-hCG, for preoperative planning." (PMID 24731683, 2014). "The univariate analysis showed that the significant prognostic factors were miR-141 expression, tumor size, tumor grade, recurrence, metastasis and serum AFP." (PMID 24551096, 2014). "Studies in HCC patients indicate that circulating AFP-specific T cells can be activated ex vivo and can recognize tumor despite high circulating serum levels of this antigen." (PMID 24708667, 2014). "Genes of fetal or embryonic origin are often re-expressed in various tumours and alpha-fetoprotein (AFP) expression has been shown to be re-activated in HCC." (PMID 25108398, 2014). "The levels of tumor markers investigated in our study (AFP and DCP) were quite high, and these markers are known to be negative prognostic factors given their association with aggressive pathological features." (PMID 25276780, 2014). "It was generally known that AFP-L3, which was the LCA-bound fraction of AFP, as a new generation of tumor marker for HCC had been widely used in clinic." (PMID 25232831, 2014).
tumor (continued). "On laboratory data alkaline phosphatase (ALP) and lactic dehydrogenase (LDH) are elevated most of the time, while tumor markers as a-fetoprotein (AFP) and carcinoembryonic antigen (CEA) remain between normal ranges." (PMID 24949208, 2014). "Tumor markers, including α-fetoprotein (AFP), cancer embryonic antigen (CEA), carbohydrate antigen 199 (CA199), and CA125 were all within normal limits." (PMID 25120715, 2014). "The present patient showed an early decrease in AFP at 18 days after the diagnosis which is consistent with the tumor shrink identified by following hepatic arteriography and CT findings." (PMID 25431715, 2014). "In this study octreotide LAR treatment induced tumour size regression, AFP level decrease and QoL improvement." (PMID 25225571, 2014). "The persistency or secondary increase of the AFP values represents a residual tumour, metastases, or a relapse." (PMID 25525545, 2014). "Both pre- and post-treatment serum AFP levels significantly correlated with recurrent tumor size (P < 0.05 for both)." (PMID 24993566, 2014). "On top of that, they also showed that tumor number and pre-operative AFP levels were significantly higher in CIMP + samples." (PMID 24635883, 2014). "The current study found that the recurrent tumor size was correlated with 3-month post-treatment serum AFP level, and that survival was correlated with tumor size and serum AFP level." (PMID 24993566, 2014). "The high nucleolin expression more frequently occurred in HCC tissues with advanced tumor stage (P = 0.001), high tumor grade (P = 0.02) and high serum AFP level (P = 0.008) than those with early tumor stage, low tumor grade and low serum AFP level." (PMID 25230759, 2014). "Here, we investigated the effect of probe molecule size on the detection of a tumor marker, α-fetoprotein (AFP) using a FET biosensor." (PMID 28788579, 2014). "Recommended surveillance strategies are based on periodic evaluation by ultrasound imaging and determination of blood levels of the tumor marker alpha-fetoprotein (AFP)." (PMID 27335840, 2014). "Tumor markers such as alpha-fetoprotein (AFP) and β-human chorionic gonadotropin (β-hCG) were negative, and hormonal investigations were normal." (PMID 25230718, 2014). "The levels of some miRNAs were dramatically associated with clinicopathologic features regarding Child-Puge class, AFP, tumor size and satellite nodules." (PMID 25275448, 2014). "Univariate analysis revealed that tumor size, tumor number, alpha-fetoprotein (AFP), des-gamma-carboxy prothrombin (DCP), and Lens culinaris agglutinin-reactive fraction of alpha-fetoprotein were significant risk predictors of vascular invasion." (PMID 25397677, 2014). "In contrast, OPN expression was unrelated to patient gender, age, number of tumors, AFP (alpha-Fetoprotein), HBsAg (Hepatitis B surface antigen), tumor grade and liver function." (PMID 24498405, 2014). "Serum AFP level has been suggested to directly reflect tumor size, and the ratio of serum AFP level to tumor diameter to predict recurrence after curative resection is better than serum AFP alone." (PMID 24993566, 2014). "We then conducted the stratified analysis based on age, serum AFP, tumor size, number of tumor lesions, PVTT status, BCLC stage and number of TACE treatment." (PMID 24718422, 2014). "Of other features, AFP level, tumor size, tumor multiplicity and vascular invasion were found to be independent prognostic predictors for poor cancer-specific survival and recurrence-free survival (P<0.05)." (PMID 24475046, 2014). "The HCC specific marker alpha fetoprotein (AFP) was also overexpressed in the tumor extract, but also in the adjacent liver presumably as a consequence of liver injury and regeneration consecutive to the graft and tumor growth." (PMID 25203629, 2014). "Our multivariate analysis showed that tumor size and serum AFP level before treatment were prognostic factors for overall survival." (PMID 24410841, 2014).
tumor (continued). "More recently, CK19 levels together with CK7 (cytokeratin 7) have been investigated again using an HCC-TMA and found to be significantly associated with tumor grade and AFP levels (alpha-fetoprotein)." (PMID 27600338, 2014). "This is because the serum AFP level reflects the tumor burden, whereas the serum PIVKA-II level reflects the extent of vascular invasion (portal vein thrombosis and extrahepatic disease extension)." (PMID 24455683, 2013). "The predictive power (in terms of survival) of the two combined tumor markers was better than that of AFP alone, and comparable to that of the radiological response, according to the mRECIST criteria." (PMID 24455683, 2013). "Currently, most practice guidelines recommend routine surveillance for HCC using ultrasonography and serum tumor markers, such as alpha-fetoprotein (AFP)." (PMID 23717429, 2013). "The tumor size was 5 cm and 3 cm for the 2 patients with normal AFP level, whereas the mean tumor size was 9.6 cm (range, 1.2-20 cm) in the other 12 patients." (PMID 23800233, 2013). "Consistent with the results, the mean tumor weight and concentration of serum AFP in TIPE2 group were also significantly lower than those of Mock group." (PMID 24274578, 2013). "Factors related to extra-subsegmental recurrence that were found to be significant by univariate Cox proportional hazard regression were age, platelet count, tumor size, AFP and AFP-L3." (PMID 23593129, 2013). "Serum α-fetoprotein (AFP) is the most commonly used circulating tumour marker, but has such low sensitivity and specificity that international guidelines no longer recommend using AFP when screening for HCC." (PMID 23527199, 2013). "Multivariate regression analyses were performed to identify which of the following factors were the predictors of the hypermethylation group: serum albumin, AFP, and tumor multiplicity." (PMID 23678400, 2013). "Other tumor-specific promoters used to drive E1-mediated virotherapy against various cancers include mucin-1 promoter, osteocalcin promoter, AFP promoter, midkine promoter, and COX-2 promoter." (PMID 23484134, 2013). "We found that in patients with a low AFP level, Cx43+ tumor tissues were an independent predictor of later recurrence and a better prognosis." (PMID 23800357, 2013). "With respect to laboratory investigations, retroperitoneal teratomas can express a diversity of serum tumor markers such as elevated alpha-fetoprotein (AFP), carcinoembryonic antigen (CEA), and CA 19-9." (PMID 23762690, 2013). "Serum tumour markers were elevated with an alpha-fetoprotein (AFP) of 28135 μg/l, beta-human chorionic gonadotropin (ß-HCG) of 19700 U/l and lactate dehydrogenase (LDH) of 4421 U/l." (PMID 23402579, 2013). "Serum levels of the tumor markers human chorionic gonadotropin and alpha-fetoprotein were normal and the CA-125 level was only moderately elevated." (PMID 23856407, 2013). "Multivariate analyses showed that PFS time was independently correlated with age (P = 0.047) and OS time was independently correlated with HBsAg positivity (P = 0.037), AFP level (P = 0.015), and tumor size (P = 0.003)." (PMID 23552472, 2013). "When the percentage declines in tumor maker levels after treatment (from pretreatment levels) were evaluated, the reductions in both AFP and PIVKA-II levels in patients exhibiting a CR or PR were significantly greater than in those with SD or PD." (PMID 24455683, 2013). "Of these, elevated ALT, Child-Pugh class, tumor size, tumor multiplicity, presence of PVT, presence of metastasis, elevated AFP, high CRP and high NLR were significantly associated with poorer survival." (PMID 23409924, 2013). "Tests for serum tumor makers including AFP, CA125, CA199, CEA, and HCG were performed in most cases." (PMID 23826706, 2013). "Tumor marker levels were as follows: alpha-fetoprotein (AFP), 88.5 nG/mL; protein induced by vitamin K absence or antagonist II (PIVKA-II), 5130 mAU/mL." (PMID 25379302, 2013).